PPTC7 (protein phosphatase targeting COQ7)
Description:
Protein phosphatase that plays an essential role in mitochondrial metabolism and biogenesis. Positively regulates biosynthesis of the ubiquinone, coenzyme Q. Dephosphorylates the ubiquinone biosynthesis protein COQ7 which is likely to lead to its activation. Serves as a crucial sensor for mitophagy, though the underlying mechanism remains ambiguous (By similarity). May dephosphorylate BNIP3 and NIX and thereby directly regulates mitophagy receptor function and stability (By similarity). Alternatively, promotes SCF-FBXL4-dependent ubiquitination and degradation of BNIP3 and NIX independently of its catalytic activity to restrain mitophagy.
Synonyms: TA-PP2C; TAPP2C
Tractability: Antibody: the Human Protein Atlas places it where antibodies can reach. PROTAC: ubiquitination databases record sites on it; its protein half-life has been measured.
Gene: Protein-coding gene on chromosome 12 (110,533,245 to 110,583,383, reverse strand). Ensembl gene ENSG00000196850.
Subcellular location: Mitochondrion matrix
Subcellular location (Human Protein Atlas): Cytosol; Plasma membrane
Gene Ontology:
Molecular function: protein binding; protein serine/threonine phosphatase activity; protein-macromolecule adaptor activity
Biological process: negative regulation of mitophagy; positive regulation of ubiquinone biosynthetic process; regulation of ubiquinone biosynthetic process
Cellular component: mitochondrial matrix; mitochondrial outer membrane; mitochondrion
Genetic constraint (gnomAD): Loss-of-function variants: 6 observed, 28.13 expected, observed/expected ratio (o/e) 0.21, 90% interval 0.12 to 0.42. The upper end of that interval is the gene's LOEUF score, 0.42, which puts it in group 1 of 6, group 1 being the genes least tolerant of losing a copy. Missense variants: 209 observed, 359.23 expected, observed/expected ratio (o/e) 0.58, 90% interval 0.52 to 0.65. Synonymous variants: 153 observed, 152.44 expected, observed/expected ratio (o/e) 1, 90% interval 0.88 to 1.15.
Homologues: Orthologues: chimpanzee PPTC7 (100% identical), dog PPTC7 (100% identical), macaque PPTC7 (99% identical), pig PPTC7 (99% identical), mouse Pptc7 (99% identical), rat Pptc7 (99% identical), guinea pig PPTC7 (95% identical), rabbit PPTC7 (93% identical), zebrafish pptc7a (92% identical), tropical clawed frog pptc7 (91% identical), zebrafish pptc7b (89% identical), Drosophila melanogaster CG12091 (51% identical), and 3 more.
Diseases named in the same sentence as PPTC7 in open-access papers:
PPTC7 is named in the same sentence as 9 diseases in open-access papers, as found by Europe PMC text mining. Sharing a sentence is not in itself a finding about the gene and the disease. The quoted sentences say what the papers report.
Hepatic steatosis (1 paper, 2023). Steatosis is a term used to denote lipid accumulation within hepatocytes. "We found that Pptc7 KO male mice did not have significantly altered ketone levels in response to an overnight fast but that both sexes of Pptc7-/- mice had significantly elevated liver triacylglycerols (TAGs), consistent with hepatic steatosis." (PMID 37833277, 2023).
infection (1 paper, 2022). The state of being infected such as from the introduction of a foreign agent such as serum, vaccine, antigenic substance or organism. "QRT-PCR confirmed that infection of the pre-miR-582 lentivirus significantly downregulated the mRNA expression of PPTC7 in all three BCP-ALL cell lines." (PMID 35514986, 2022).
PPTC7 also shares sentences with these, for which no sentence is quoted: cancer (1 paper); glutaric aciduria type II (1); hyperprolinemia (1); Hypoglycemia (1); lactic acidosis (1); leukodystrophy (1); Obesity (1).